CXCR4 (C-X-C motif chemokine receptor 4)
Diseases named in the same sentence as CXCR4 in open-access papers (continued):
Sharing a sentence is not in itself a finding about the gene and the disease.
neuroblastoma (continued). "In a separate study, authors have shown that MSCs can upregulate CXCR4 expression and can induce invasiveness in neuroblastoma cell lines." (PMID 32722460, 2020). "Several factors can modulate the chemokine receptor repertoire on immune cells: For instance, conditioning human NK cells with TGFβ1, derived from neuroblastoma cells, significantly upregulated CXCR4 and CXCR3 expression and downregulated CX3CR1 on NK cells." (PMID 30319622, 2018). "In neuroblastoma, CXCR4 surface expression classes can be identified according to the expression levels of different isoforms." (PMID 29515781, 2018). "Here, we show that CXCR4 antagonist expression from an oncolytic vaccinia virus delivered intravenously to mice with neuroblastoma tumors augmented efficacy of the DC vaccines compared to treatments mediated by a soluble CXCR4 antagonist or oncolysis alone." (PMID 30149659, 2018). "The pivotal role of the (SDF-1)/CXCR4 axis in BM metastasis has been described for various tumor types, including neuroblastoma." (PMID 29867502, 2018). "The 55 kDa, 67 kDa, and 87 kDa isoforms correlated with high expression of CXCR4 on the cell surface in neuroblastoma cell lines but were also seen in some cell lines that showed low expression levels of CXCR4 on the cell surface." (PMID 29515781, 2018). "Based on that, we postulate that BK, secreted by the BM, enhances adhesion, invasion, angiogenesis and sensitizes CXCR4 to promote metastasis of neuroblastoma cells to the BM." (PMID 29867502, 2018). "CXCR4 is overexpressed in blood, breast, prostate, lung, and colon cancer, as well as in neuroblastoma and peripheral nerve sheath tumors." (PMID 29515781, 2018). "TGF-β1 produced by neuroblastoma cell lines was shown to upregulate the surface expression of CXCR4 and CXCR3 on both CD56high and CD56low NK cells, while it downregulated CX3CR1 in the CD56low subset." (PMID 27766097, 2016). "Neuroblastoma cell lines showed heterogeneity in the expression levels of CXCR4 with SJ-N-KS showing the highest expression level and SMS-KAN showing the least." (PMID 25774696, 2015). "The expression rate of CXCR4 positive was 70.0% (56/80) in the neuroblastoma group, which was significantly higher than the rate of 25.0% (3/12) in the ganglioneuroma group, and the difference between the two groups was statistically significant (P=0.0008)." (PMID 25503960, 2015). "Using immunohistochemistry, NF-κB and CXCR4 were significantly correlated with each other (P=0.0052, Fisher’s exact test) in a cohort of neuroblastoma samples (n=80)." (PMID 25503960, 2015). "We found a correlation between the expression of the 47kDa isoform of CXCR4 and increased invasive potential towards mRPMI in neuroblastoma." (PMID 25774696, 2015). "Previous studies using cell lines and primary cancer samples have shown correlations between high CXCR4 expression levels on neuroblastoma cells and increased occurrence of bone marrow metastases." (PMID 25774696, 2015). "Overexpression of CXCR4, whose involvement in various human tumors is well known, was frequently observed in neuroblastoma tissues to increase neuroblastoma metastasis." (PMID 25503960, 2015). "We found an isoform-specific-over-expression of CXCR4, in neuroblastoma cell lines, upon exposure to the MSC secretome, and a protective role of the MSC secretome in the expression of the 47 kDa CXCR4 isoform." (PMID 25774696, 2015). "In the present study, the expression of CXCR4 and NF-κB was examined in a subset of neuroblastoma tumors and correlative analyses were conducted with clinicopathological variables." (PMID 25503960, 2015). "Taken together, these findings led to the conclusion that TNF-α partially functions through the NF-κB signaling pathway to upregulate CXCR4 expression to foster neuroblastoma metastasis." (PMID 25503960, 2015). "This up-regulation of 47 kDa CXCR4, can be considered as one of the initial steps in the sequential and specific metastasis process in neuroblastoma." (PMID 25774696, 2015).
neuroblastoma (continued). "In conclusion, this study suggests a modulatory role of the MSC secretome in the selective expression of the 47 kDa CXCR4 isoform, and in the bone marrow metastasis of neuroblastoma cells." (PMID 25774696, 2015). "A significant reduction in the levels of secreted MMP-9, compared to control levels, was observed in neuroblastoma cell lines treated either with AMD 3100 or with anti-47 kDa CXCR4 neutralizing antibody." (PMID 25774696, 2015). "The present study indicates that the inflammatory cytokine, TNF-α, partially functions through the NF-κB signaling pathway to upregulate CXCR4 expression to foster neuroblastoma cell metastasis." (PMID 25503960, 2015). "As the levels of CXCR4 appeared to correlate with NF-kB-p65 expression in neuroblastoma tumor samples, the role of NF-κB-p65 on CXCR4 expression was investigated in vitro." (PMID 25503960, 2015). "We found an isoform-specific over expression of CXCR4 in neuroblastoma cells triggered by the MSC secretome." (PMID 25774696, 2015). "TNF-α was also shown to induce CXCR4 expression in neuroblastoma cells in a time- and dose-dependent manner." (PMID 25503960, 2015). "In the present study, there was a significant positive correlation between the expression status of NF-κB-p65 and that of CXCR4 in neuroblastoma tissues." (PMID 25503960, 2015). "The inhibitor of NF-κB reduced CXCR4 expression on neuroblastoma cells and resulted in decreased migriation towards SDF-1α in response to TNF-α." (PMID 25503960, 2015). "In this study, we have investigated the expression of CXCR4 on 20 different neuroblastoma cell lines, and classified them on the basis of their invasive potential and CXCR4 expression profile." (PMID 25774696, 2015). "Our data suggest a modulatory role of the MSC secretome on the expression of the 47 kDa CXCR4 isoform and invasion potential of the neuroblastoma cells to the bone marrow." (PMID 25774696, 2015). "In our study, we found that human-MSC secretome up-regulated the expression of CXCR4, especially that of the 47 kDa isoform in neuroblastoma." (PMID 25774696, 2015). "The aim of this study is to understand the effect of MSC-secretome on the expression of CXCR4 and the metastatic potential of neuroblastoma cell lines." (PMID 25774696, 2015). "Further, the neuroblastoma cell membrane was found to predominantly express the 47 kDa CXCR4 isoform, suggesting its role in CXCR4 mediated bone marrow metastasis in neuroblastoma." (PMID 25774696, 2015). "Immunoprecipitated CXCR4 from serum-starved or mRPMI pre-treated neuroblastoma cells were subjected to western blot analysis for the determination of CXCR4 isoforms." (PMID 25774696, 2015). "The frequently used neuroblastoma cell line SH-SY5Y showed a relative high CXCR4 mRNA level but was CXCR7-negative." (PMID 24770893, 2014). "In neuroblastoma, CXCR4 surface expression requires ubiquination and oligomerization of the receptor." (PMID 24559071, 2014). "Our in vitro results suggest that in neuroblastoma cells CXCR4 in combination with overexpression of PGK1 also plays a role in cell proliferation." (PMID 24376734, 2013). "It has been proposed that the chemokine receptor CXCR4 is involved in the mechanisms by which neuroblastoma cells metastasize to specific sites." (PMID 24376734, 2013). "It was suggested that neuroblastoma cell homing to the bone marrow is influenced by the various interactions of the chemokine receptor CXCR4 and its ligand, the stromal cell-derived factor-1 (SDF1)." (PMID 24376734, 2013). "A higher expression of CXCR4 was found in primary neuroblastoma from patients with high-stage disease and in patients with bone marrow metastases." (PMID 24376734, 2013). "PGK1 expression significantly positively correlates with CXCR4 expression, which is known to be an important player in the tumor biology of neuroblastoma, and tumor dissemination to the bone marrow." (PMID 24376734, 2013).
neuroblastoma (continued). "PGK1 expression positively correlates with CXCR4 expression in neuroblastoma patients and is downregulated by inhibition of CXCR4 in neuroblastoma cells." (PMID 24376734, 2013). "Taken together, these data show that regulation of CXCR4 surface expression in neuroblastoma cells can occur independently of SDF-1 contribution arguing against an autocrine mechanism." (PMID 20028517, 2009). "In light of these findings the extent to which basal CXCR4 surface expression occurs in neuroblastoma cells and the significance in of this expression on the biology of these tumors has not been conclusively demonstrated." (PMID 20028517, 2009). "Taken together, our data show that CXCR4 is widely expressed at variable levels on the surfaceof patient-derived neuroblastoma cell lines." (PMID 20028517, 2009). "Autocrine downregulation of CXCR4 by endogenously derived SDF-1 in the extracellular medium has previously been suggested to explain the low levels of CXCR4 seen on some neuroblastoma cell lines." (PMID 20028517, 2009). "In an effort to further evaluate proteasomal-mediated targeting of CXCR4 as a possible mechanism for regulating its surface expression, neuroblastoma cells were treated with the irreversible proteasome inhibiting agent Lactacystin." (PMID 20028517, 2009). "Further work will focus on identifying the nature of the CXCR4 modifications that exist in neuroblastoma cells and the extent, if any, to which these isoforms regulate the various CXCR4 mediated responses." (PMID 20028517, 2009). "In light of observing posttranslational modification of CXCR4 with ubiquitin in neuroblastoma cells we decided to examine what effect if any, treatment with the irreversible proteasome inhibitor lactacystin would have on surface expression of CXCR4." (PMID 20028517, 2009). "Despite its obvious importance in the progression of several forms of cancer, the role and nature of CXCR4 function in neuroblastoma biology is less clear." (PMID 20028517, 2009). "It had previously been suggested that surface expression of CXCR4 on neuroblastoma cells was subject to SDF-1 mediated down-regulation via a negative autocrine loop mechanism." (PMID 20028517, 2009). "Additionally, Klein and colleagues provided interesting in vitro and in vivo data describing how CXCR4 signaling controls neuroblastoma tumor growth and response to therapy." (PMID 36980182, 2023). "SDF-1 binds to the cognate receptor CXCR4 expressed on cancer cells including neuroblastoma." (PMID 33838662, 2021). "Whether SDF-1/CXCR4 axis is a vital modifier in MSCs homing towards neuroblastoma, like it is described in the trafficking towards injured tissues remains uncertain." (PMID 33838662, 2021). "It was also reported that MSCs secretome could modulate CXCR4 expression and invasion to the bone marrow of neuroblastoma in vitro." (PMID 33838662, 2021). "Finally, neuroblastoma cells have been shown to upregulate CXCR4 and CXCR3 and reduce CX3CR1 expression on NK cells via the release of TGF-β." (PMID 32272610, 2020). "Similarly, neuroblastoma cells have been shown to upregulate CXCR4 and CXCR3 on both CD56dim and CD56bright NK cells and to reduce CX3CR1 (which is important for NK cell extravasation) on CD56dim NK cells viarelease of TGF-β." (PMID 32272610, 2020). "The expression of CXCR4 correlated with the bone marrow metastasis in primary neuroblastoma tumors." (PMID 32722460, 2020). "However, SDF-1 dose-dependent migration of neuroblastoma was observed only when CXCR4 expression and activity had been upregulated." (PMID 29867502, 2018). "Furthermore, there were found exclusively in neuroblastoma cell lines that showed low expression of CXCR4 on the cell surface." (PMID 29515781, 2018). "Thus, we here propose the existence of other mechanisms regulating neuroblastoma trafficking to the BM and/or increasing responsiveness of neuroblastoma to SDF-1 by sensitization or overexpression of the CXCR4." (PMID 29867502, 2018).
neuroblastoma (continued). "Regarding modulation of CXCR4 expression using pharmacological agents, tyrosine kinase inhibitors (TKIs) imatinib and nilotinib have been shown to selectively increase the cell surface of CXCR4 on NK cells and monocytes, in vitro experiments using NK cells derived from neuroblastoma patients." (PMID 30319622, 2018). "This regulatory role of the MSC secretome on the expression of the invasion-specific 47 kDa CXCR4 isoform could be a molecular target in the treatment of advanced neuroblastoma." (PMID 25774696, 2015). "Invasion potential and CXCR4 isoforms expressed in neuroblastoma cell lines." (PMID 25774696, 2015). "In order to study whether total CXCR4 expression had any role in determining the invasive potential of neuroblastoma cell lines, the total CXCR4 expression was assayed by flow-cytometry." (PMID 25774696, 2015). "Western blot analysis of whole cell lysates from the CXCR4 blocking experiment showed reduced expression of integrin α3 and integrin β1, both of which are deemed to be important in the initial stages of metastasis in neuroblastoma." (PMID 25774696, 2015). "In order to assess whether any specific isoform of CXCR4 might be responsible for the highly invasive phenotype in neuroblastoma, western blot detection of CXCR4 isoforms using a polyclonal anti-CXCR4 antibody was carried out." (PMID 25774696, 2015). "Exogenous ubiquitination of CXCR4, rendering the CXCR4 inactive with respect to metastasis, might also be considered as a promising target in neuroblastoma treatment." (PMID 25774696, 2015). "Other studies have also shown that CXCR4 supports establishment of neuroblastoma primary tumors." (PMID 25774696, 2015). "Finally, the interaction of the tumor cells with macrophages was shown to enhance CXCR4 expression in the neuroblastoma cells in an NF-κB-dependent manner." (PMID 25503960, 2015). "Further, it could be inferred that the 47 kDa isoform is the active form of CXCR4 in neuroblastoma cell lines, and the presence of this isoform in the cell might explain the highly invasive phenotype." (PMID 25774696, 2015). "Notably, there was a positive correlation between the expression of NF-kB-p65 and CXCR4 in the 80 neuroblastoma samples (P=0.0052, Fisher’s exact test)." (PMID 25503960, 2015). "In this study, we explored the MSC secretome—tumor interactions, and for the first time demonstrated a positive regulation of the 47 kDa CXCR4 isoform, in neuroblastoma, which might be a key step in the process of metastasis." (PMID 25774696, 2015). "Western blot analysis revealed the expression of multiple CXCR4 isoforms in neuroblastoma cells." (PMID 25774696, 2015). "Furthermore, the inflammatory cytokine TNF-α acts as a regulator of functional CXCR4 expression on neuroblastoma cells in a NF-κB-dependent manner." (PMID 25503960, 2015). "Therefore, additional investigations would be necessary to better understand the role of CXCR4—CXCL12 axis in neuroblastoma biology." (PMID 25774696, 2015). "Targeting inflammatory cytokines or NF-κB signaling pathways, and ultimately CXCR4, may be a therapeutic strategy in neuroblastoma." (PMID 25503960, 2015). "The present data suggests that the TNF-α-activated NF-κB/CXCR4/SDF-1α pathway may be a potential regulator of neuroblastoma cell metastasis." (PMID 25503960, 2015). "Since, the 47 kDa CXCR4 isoform is expressed only in the highly invasive cell lines, it may be used as a marker for bone marrow metastasis in neuroblastoma." (PMID 25774696, 2015). "Reduced integrin α3 β1 expression, could be directly related to reduced MMP-9 secretion and lower invasiveness of neuroblastoma cells, under conditions of CXCR4 blockage." (PMID 25774696, 2015). "In conclusion, the present study demonstrates that CXCR4 and Foxp3 exhibit higher expression in neuroblastoma cells, and therefore, exposure to chemotherapy agents may reduce their expression." (PMID 24932293, 2014).
neuroblastoma (continued). "However, the role of CXCR4 in neuroblastoma and its response to chemotherapy remain largely unclear." (PMID 24932293, 2014). "Thus, the present study aimed to examine the expression of CXCR4 and Foxp3 in neuroblastoma cell lines LAN-5 and SK-N-SH." (PMID 24932293, 2014). "Although the abnormal expression of CXCR4 and Foxp3 may be involved in the metastasis and immune evasion of other types of tumors, their role in neuroblastoma and their response to chemotherapy remain largely unclear." (PMID 24932293, 2014). "PGK1 is downregulated by inhibition of CXCR4 in neuroblastoma cells." (PMID 24376734, 2013). "Recent reports indicate that CXCR4 is commonly expressed on neuroblastoma metastases in the bone marrow and that it may be actively contributing to neuroblastoma tumor cell homing to the bone marrow." (PMID 24376734, 2013). "SDF-1/CXCR4 axis is involved in the promotion of angiogenesis, local cell proliferation and migration of cancer cells to the metastatic sites in many different kinds of cancers as those of breast, lung, ovarian, renal, prostate, and neuroblastoma." (PMID 22417013, 2012). "The purpose of this study was to evaluate the expression of CXCR4 in neuroblastoma cells and determine to what extent, if any, expression of this receptor may contribute to the heterogeneity associated with the disease." (PMID 20028517, 2009). "The extent of difference observed when transcriptional and surface expression levels from the same cell line are compared however suggests that some post-transcriptional/translational event is involved in regulating the final expression of CXCR4 on the surface of neuroblastoma cells." (PMID 20028517, 2009). "Analysis of results from this data set identified CXCR4 as one of the genes differentially overexpressed in metastatic compared to localized primary tumors obtained at diagnosis, supporting a role for CXCR4 in neuroblastoma dissemination." (PMID 20028517, 2009). "Additionally these data suggest that post-translational modifications of CXCR4, in part through direct ubiquitination, can influence trafficking of CXCR4 to the surface of neuroblastoma cells in a ligand-independent manner." (PMID 20028517, 2009). "In an effort to further assess CXCR4 expression patterns in neuroblastoma and the correlation of such patterns with tumor progression, global expression of CXCR4 in neuroblastoma cells was analyzed at the transcriptional, translational, and surface expression level." (PMID 20028517, 2009). "We hypothesized that the differential expression of CXCR4 in neuroblastoma cells might be due to post-translational modifications that influenced its trafficking to the cell surface." (PMID 20028517, 2009). "Recent work has demonstrated that expression of CXCR4 in neuroblastoma cells can be differentially regulated by exposure to stromal components, and that the nature of this regulation can vary dependent on both the cell line being examined and the tissue origin of the stroma." (PMID 20028517, 2009). "CXCR4 has been shown to mediate proliferation of neuroblastoma cells under certain conditions." (PMID 20028517, 2009). "Moreover, CXCR4 expression in neuroblastoma primary tumors is significantly correlated with the pattern of metastatic spread." (PMID 15978137, 2005). "In NB patients, high CXCR4 expression correlates with tumor cell migration and bone marrow metastasis, often described as ‘neuroblastoma metastatic cell homing’." (PMID 36980635, 2023). "BK-mediated effects on neuroblastoma progression include increasing cell adhesion, promoting angiogenesis, and rearrangement of the cytoskeleton, in addition to proliferation induction and enhancement of neuroblastoma invasion capacity due to sensitization of both CXCR4 and P2X7B receptors." (PMID 29867502, 2018).